IL6 (interleukin 6)
Diseases named in the same sentence as IL6 in open-access papers (continued):
Sharing a sentence is not in itself a finding about the gene and the disease.
COVID-19 (continued). "Excessive IL-6 levels are highly correlated with the lethal complications of COVID-19 patients." (PMID 33014208, 2020). "The inhibition of HLA-DR expression was performed by plasma of COVID-19 patients, and it could be partially restored via IL-6 blocker." (PMID 33194800, 2020). "More importantly, IL-6 is a major functional marker of cellular senescence, and the age-dependent enhancement of the IL-6 amplifier may correspond to the age-dependent increase of COVID-19 mortality." (PMID 33329533, 2020). "Based on this theory, a number of anti-cytokine and antiinflammatory therapies are being tested in COVID-19, including anti–IL-6(R) antibodies, IL-1 receptor antagonists, and JAK/STAT inhibitors, with early trial results failing to demonstrate significant efficacy." (PMID 32687484, 2020). "Partly corresponding to Wei’s team, our clinical study found that the serum level of IL-6 decreased significantly before discharge, which may reflect the pro-inflammatory role of IL-6 in the course of COVID-19 from another perspective." (PMID 32983180, 2020). "In fact, high IL-6 level has been identified as a predictor of COVID-19 mortality, it was reported recently that IL-6 trans-signaling may be responsible for infiltration of granulocytes and monocytes and dame in lung tissue in cases with SARS-CoV-2 infection." (PMID 33072191, 2020). "The peripheral blood levels of CCL5 were elevated before IL-6 in severe COVID-19 patients." (PMID 32766256, 2020). "Severe COVID-19 patients show a notable elevation of inflammatory cytokines such as IL-2R, IL-6, granulocyte colony-stimulating factor (GCSF), macrophage chemotactic protein-1 (MCP1), macrophage inflammatory protein (MIP)1A, TNF-α and anti-inflammatory compounds such as CRP." (PMID 32876941, 2020). "If IL-6 is responsible for CRS in COVID-19, it is unknown at what level or time point it changes from having anti-viral properties to causing immunopathology." (PMID 33051534, 2020). "Similarly, cytokine storm is also a common feature of severe cases in COVID-19, and elevated levels of serum IL-6 and CRP correlate with respiratory failure, ARDS, MOF and adverse clinical outcomes." (PMID 33329533, 2020). "Because interleukin 6 (IL-6) is known to play a key role in inflammation, IL-6 receptor inhibitors such as tocilizumab may potentially treat COVID-19 by attenuating cytokine release." (PMID 32635353, 2020). "Additionally, LIGHT induces the release of other inflammatory cytokines, including IL-6 and granulocyte-macrophage colony-stimulating factor (GM-CSF), which are reported at elevated levels in COVID-19 patients." (PMID 32817460, 2020). "There are complexities with the targeting of IL-6 in COVID-19." (PMID 32629875, 2020). "Severe COVID-19 is largely the result of a dysregulated immune response characterized by lymphocytopenia, neutrophilia and critical hypercytokinemia, or “cytokine storm,” which is largely mediated by the cytokine interleukin-6 (IL-6)." (PMID 33194450, 2020). "IL-6 is known to increase the rate of fibrotic clot formation, so it also may play a role in the thrombotic complications observed in COVID-19." (PMID 33194450, 2020). "It appears that infection with COVID-19 can stimulate a positive feedback cycle of increased IL-6 and decreased GSH that may explain the cytokine storm that can accompany this infection." (PMID 32992775, 2020). "In that study, the authors found a correlation between COVID-19 severity and the IL-6:AAT ratio." (PMID 33276468, 2020). "Though our result was consistent with that of these studies, this large-sample study gives general profiles of baseline IL-6 distribution among patients with common, severe and critical subsets, suggesting a strong correlation between IL-6 level and severity of COVID-19." (PMID 33121497, 2020). "The mechanism may be related to the rapid and massive production of various cytokines such as TNF-, IL-6, IL-1, and IL-8 in body fluids when patients were infected with COVID-19." (PMID 33013395, 2020).
COVID-19 (continued). "Severe lung and systemic inflammation is believed to result from cytokine dysregulation; in patients with SARS elevated levels of cytokines such as TNF, CXCL10, IL-6, and IL-8 likely contributed to the poor outcome, strikingly similar to cytokine storm reported in severe COVID-19 patients." (PMID 33133083, 2020). "Multiple anti-inflammatory agents are thus currently undergoing clinical evaluation for COVID-19, including not only corticosteroids but also biologicals that target inflammatory cytokines, such as anti-IL-6 or anti-IL-1β agents, and other immune-modulatory agents." (PMID 33194755, 2020). "In this report, we conclude that elevated IL-6 level in a COVID-19 patient is not necessarily associated with severe COVID-19." (PMID 33304877, 2020). "Among these cytokines, interleukin-6 (IL-6) is elevated in patients with COVID-19." (PMID 32530389, 2020). "Finally, clinical studies showed that the level of IL6 was elevated in COVID-19 patients, and DYY can reduce its levels." (PMID 32536965, 2020). "In the present studies, we have provided evidence that while IL-6 may be used for the diagnosis of severe COVID-19 patients, IL-8 is overall a better biomarker for the COVID-19 disease prognosis." (PMID 33488599, 2020). "However, the levels of IL-6 in those who developed severe COVID-19 were significantly higher than in patients with DHF, and in one of the patients who succumbed to the illness had values of 2179.7 ng/L, 24 h before death." (PMID 33199778, 2020). "The leading role of IL-6 in this process was also demonstrated in COVID-19." (PMID 33114676, 2020). "Another systematic review including 11 case reports of COVID-19 patients indicated that tocilizumab could effectively inhibit the hyper-inflammatory state by downregulating the level of IL-6 and CRP level." (PMID 34765999, 2020). "Taken together, we demonstrate that CXCL10 is an important cytokine secreted from infected airway epithelial cells, and that these cells are unlikely to be the source of classic pro-inflammatory cytokines such as IL-6 and TNFα reported to be elevated in the systemic circulation of COVID-19 patients." (PMID 33284849, 2020). "However, there are a number of differences between severe COVID-19 and CRS, such as lower IL-6 levels and death caused by respiratory failure and thrombosis, rather than from circulatory failure and status epilepticus, as seen in CRS." (PMID 32838342, 2020). "Consequently, there are clinical trials involving anti-IL-6 therapies for the treatment of COVID-19 that are actively recruiting." (PMID 32797326, 2020). "Increased levels of stress or IL-6 have also been described in SARS or COVID-19 patients." (PMID 32574266, 2020). "Similarly, another study found that the combination of IL-6 and D-Dimer measurements had the highest specificity and sensitivity for early prediction of the severity of COVID-19 patients (~94%), and that they were also useful to track pneumonia development." (PMID 33072097, 2020). "In that sense, it has been reported that the host genetic polymorphisms such as ABO, Human Leukocyte Antigen (HLA), IL-6, complement and angiotensin-converting enzyme 2 (ACE-2) genes may be associated with SARS-CoV-2 susceptibility and COVID-19 severity." (PMID 33584667, 2020). "Indeed, controlled clinical trials are underway around the world to test the treatment of IL-6 and IL-6R antagonists for COVID-19 patients with severe respiratory complications." (PMID 33178109, 2020). "IL-6, often abnormally elevated in the circulation of patients with severe COVID-19, is a pro-inflammatory cytokine produced by activated monocytes, macrophages, endothelial cells and other cells that has pleiotropic effects and plays a critical role in hemostasis." (PMID 32629875, 2020). "The IL-6 is one of the major cytokines involved in acute inflammation and was already found to be significantly elevated in severe COVID-19 patients." (PMID 33584335, 2020).
COVID-19 (continued). "Notably, IL-1α induces IL-6 expression, which has emerged as a promising target for COVID-19 treatment." (PMID 33003552, 2020). "Therefore, as shown in many studies, IL-6 appears to play a significant role in the pathogenesis of severe COVID-19 compared to DHF." (PMID 33199778, 2020). "Thus, considering a robust increase in IL-6 levels in the majority of the severe COVID-19 patients, currently, treatments are underway to lower the levels of this pleiotropic cytokine." (PMID 33335518, 2020). "High levels of cytokines like IL-6, or Interferon-y could be measured in the serum of COVID-19 patients, hinting toward a dysbalanced, overreacting immune system." (PMID 32983106, 2020). "COVID-19 patients commonly present intense pro-inflammatory markers activation such as IL-1, IL-6, IL-17, IL-18, IFN, and C-reactive protein with deep lymphopenia and substantial mononuclear cell infiltration in the lungs, heart, lymph nodes, spleen, and kidney." (PMID 32849309, 2020). "Early data from the COVID-19 outbreak has shown that the complications from the disease are partly due to increases in various cytokines, including IL-6, and that elevated IL-6 levels may be associated with worse outcomes." (PMID 33469465, 2020). "Vitamin D3 has a decisive role in the regulation of the innate and adaptive immune responses implying that adequate intake of vitamin D3 may protect patients with COVID-19 at least, in part by inhibiting the excess production of IL-6 and TNF-α." (PMID 33390994, 2020). "However, we observed a more unbalanced inflammatory/anti-inflammatory cytokine response in COVID-19 patients, as reflected by the IL-6:IL-10 and TNF-α:IL-10 ratios." (PMID 33272291, 2020). "The results obtained from this study suggest that COVID-19 mortality might be due to virus-activated “cytokine storm syndrome”, considering that the plasma levels of IL-6 were higher in deceased patients compared to in discharged subjects." (PMID 32354030, 2020). "Nevertheless, in COVID-19 patients, we observed higher IL-6:IL-10 and TNF-α:IL-10 ratios that could reflect an unbalanced overproduction of IL-10." (PMID 33272291, 2020). "A potential therapy targeting the host immune system in COVID-19 might be the cytokine blockade of IL-6." (PMID 32714386, 2020). "Interleukin-6 (IL-6), downstream of NF-kB, is over-produced in COVID-19 patients." (PMID 32797326, 2020). "In terms of COVID-19, it is interesting that the aging lung is characterized by a state of heightened basal inflammation, with levels of IL-6, amongst other cytokines, significantly higher in the BALF of healthy older adults when compared to their younger counterparts." (PMID 33123152, 2020). "Due to the elevated levels of IL-2R and IL-6 accompanied by the advancement of COVID-19, several cytokines secreted by T helper type 2 (Th2) cells that could neutralize the inflammatory responses including IL-4 and IL-10." (PMID 32822430, 2020). "For patients with mild COVID-19, a high monocyte count and slight increase of IL-6 might be helpful for eradicating the SARS-CoV-2 infection and were associated with recovery from COVID-19." (PMID 32983157, 2020). "Cytokines as IL-6 have been directly related to the most aggressive form of COVID-19." (PMID 32549073, 2020). "The levels of IL-6 and IL-10 were higher in severe COVID-19 compared with those in active AOSD." (PMID 33552062, 2020). "While inhibition of IL-6 with tocilizumab appears to be efficacious and safe in preliminary investigation, the results of several ongoing clinical trials should be wait to better define the role of tocilizumab in COVID-19 prior to routine clinical application." (PMID 33244382, 2020). "Univariate analysis showed that erythrocyte count, hemoglobin level, neutrophil counts, LDH, procalcitonin, CRP, and IL-6 may be factors that affect the adverse clinical outcome of COVID-19." (PMID 33192519, 2020). "In fact, IL-6 plays a crucial pathogenetic role in pulmonary injury induced by COVID-19." (PMID 32765279, 2020).
COVID-19 (continued). "In line with this, the IL-6 blocker tocilizumab has been proposed as a treatment in COVID-19 and could increase the lymphocyte blood count of COVID-19 patients." (PMID 33267871, 2020). "The pro-inflammatory cytokine IL-6 seems to be critically high in severe COVID-19 patients." (PMID 32471272, 2020). "IL-6 may play a key role in driving the inflammatory response that leads to morbidity and mortality and patients with COVID-19 who develop ARDS." (PMID 33299621, 2020). "Moreover, we have demonstrated that inflammatory parameters, including SAA, PCT, CRP, hsCRP and IL-6 fluctuated with the deterioration of COVID-19." (PMID 33172355, 2020). "IL-6 blood measurements seem useful to diagnose severe COVID-19 cases." (PMID 32256705, 2020). "This suggests that Tocilizumab may in fact counteract the cytokine storm seen in COVID-19, by decreasing activity of IL-6." (PMID 33469465, 2020). "The results were obtained for NLR (OR: 4.6, 95% Cl: 1.242–17.80), IL-6 (OR: 6.625, 95% Cl: 2.398–18.304), IL-8 (OR: 6.881, 95% Cl: 2.453–19.298), and age (OR: 4, 95% Cl: 1.493–10.714) with our patient cohort as predictive factors for severe COVID-19." (PMID 32484453, 2020). "Some ongoing clinical trials are testing the efficacy of commercial anti-IL-6R (Tocilizumab/Actemra; Sarilumab/Kevzara) and anti-IL-6 antibody (Siltuximab/Sylvant) on COVID-19 patients used in conjunction with other therapeutic combinations (antiviral drugs and oxygen therapy)." (PMID 33426096, 2020). "In summary, we speculate that DYY may play an anti-inflammatory and immunoregulatory role in COVID-19 by acting on multiple target proteins, such as IL6, ILIB, and CCL2." (PMID 32536965, 2020). "Based on our current study, we propose the possibility that IL-6 blockade may constitute a novel therapeutic strategy for severe and critical COVID-19 patients." (PMID 32475230, 2020). "Additionally, circulating IL-6 levels are negatively correlated to monocyte HLA-DR expression, and both monocytes and CD4+ T cells were found to be circulating sources of IL-6 in COVID-19 patients." (PMID 32556942, 2020). "IL6, a pleotropic cytokine, was shown to be elevated in critically ill COVID-19 patients." (PMID 32511341, 2020). "In addition, inflammatory biomarkers, such as interleukin-6 (IL-6), can be detected in COVID-19 patients." (PMID 33167445, 2020). "Notably, one of the major activators of JAK/STAT signaling is the cytokine IL-6, which has been reported to be dramatically increased in COVID-19 patients, with a strong implication in acute inflammation and cytokine storm." (PMID 32467561, 2020). "Several clinical trials of IL-6 inhibitors for severe COVID-19 patients are conducted." (PMID 33364959, 2020). "Other similarities include cysteine-rich areas on the hepcidin and spike protein, use of furin for activation, the overarching connection between IL-6 and hepcidin and COVID-19 symptoms, and similarities between COVID-19 and altitude illness-related hypoxia, the result of elevated hepcidin." (PMID 38624521, 2020). "Corticosteroids are frequently used to treatment persons with these coronavirus infections in order to counteract high interleukin-6 concentrations, although some studies are still uncertain about the real efficacy and benefit of the use of corticosteroids in COVID-19 patients." (PMID 32883368, 2020). "An IL-6 inhibitor used for moderate to severe active rheumatoid arthritis that is not responding to other therapies.Proposed to reduce the cytokine storm in COVID-19.Adverse effects: elevation of liver enzymes and an increased risk of reactivation of other respiratory infections." (PMID 34192121, 2020). "Accordingly, serum levels of IL-6 are lower in COVID-19 compared to other CRS." (PMID 33123149, 2020).
COVID-19 (continued). "The cytokine storm in COVID-19 results in IL-6 dependent alterations in the expression of vascular endothelial growth factor and E-cadherin expression on endothelial cells contributing to vascular leakage and pulmonary hypertension, and respiratory distress in COVID-19 patients." (PMID 33613275, 2020). "Deceased COVID-19 patients had significantly higher IL-6 expression than the survivors of COVID-19." (PMID 33986658, 2020). "Based on these findings, approved drugs inhibiting IL-6/JAK/STAT signaling may represent a valuable tool in the treatment of COVID-19." (PMID 33489899, 2020). "Inflammatory/infection markers (ESR, CRP, LDH, and PCT, but not IL-6), coagulation function tests (fibrinogen, PT, and D-dimer), and glucose were positively associated with the COVID-19 severity." (PMID 32746929, 2020). "The findings suggest that IL-6 and D-Dimer level can be used to estimate the severity of COVID-19." (PMID 32256705, 2020). "The optimum critical point of IL-6 was determined as 24.3 pg/ml in severe COVID-19 group." (PMID 33195318, 2020). "A recent retrospective, multicenter study of 150 confirmed COVID-19 cases in Wuhan, China, reported poor outcomes of patients with elevated ferritin and IL-6, suggesting virally driven hyperinflammation may be associated with mortality." (PMID 32664932, 2020). "An analog of rapamycin decreased serum IL-6 and improved T cell function in older adults with T cell senescence, indicating that rapamycin may be suitable for use in older COVID-19 patients." (PMID 33510644, 2020). "As such, the increase of IL-6 to some extent may exert a beneficial effect on infected patients, especially in the later immunodeficient stage of COVID-19." (PMID 33584679, 2020). "Interestingly, upon ssRNA stimulation, COVID-19 neutrophils produced significantly higher amounts of IL-6 than healthy neutrophils." (PMID 33003471, 2020). "Being suggested as a COVID-19 severity predictor, IL-6 inhibitors may reduce the cytokine storm syndrome, especially in critically ill patients." (PMID 33425279, 2020). "Endogenous interleukin-1 (IL-1, a pro-inflammatory cytokine) potently induces IL-6 in monocytes and macrophages and is elevated in patients with COVID-19, MAS, and other conditions such as severe chimeric antigen receptor T-cell (CAR-T) mediated cytokine release syndrome (CRS)." (PMID 32775090, 2020). "Hence, blocking IL-6 activity to reduce COVID-19 severity has been proposed and clinical trials are ongoing to analyze the efficacy of therapeutic antibodies against IL-6 (siltuximab) or IL-6 receptor (tocilizumab and sarilumab)." (PMID 32948238, 2020). "Since IL-6 is the central cytokine in COVID-19 pathology as well, CAR-NK cells could provide antiviral responses without inducing the same inflammatory cytokines." (PMID 32845937, 2020). "In spite of efficient B-cell depletion expected by the anti-CD20 infusion, the patient upon COVID-19 additionally presented with normal leucocyte and lymphocyte counts, elevated C-reactive protein, a slight increase in interleuchin-6 (IL-6) levels, and moderate IgG hypogammaglobulinemia." (PMID 32512702, 2020). "Of note, high levels of pro-inflammatory cytokine and IL-6 were noted in severe COVID-19 patients." (PMID 33364959, 2020). "In this regards, bioactive phytochemicals, such as polyphenols may become promising tools for the treatment of COVID-19 in reducing the hyperactivation of cytokines such as TNFα, IL-1β, IL-6, and IL-8." (PMID 33322757, 2020). "In COVID-19, the question of whether elevated IL-6 levels reflect an overwhelming viral infection or directly cause immunopathology responsible for a patient’s poor outcome remains unanswered." (PMID 33051534, 2020). "Inhalation of Idelalisib may result in suppression of Caspase-1, IL-1, and IL-6 by blocking PI3Kδ and may therefore have a strong anti-inflammatory effect on COVID-19." (PMID 32973818, 2020).